CRP (C-reactive protein)
Diseases named in the same sentence as CRP in open-access papers (continued):
Sharing a sentence is not in itself a finding about the gene and the disease.
myocarditis (continued). "Patients with myocarditis had greater neutrophil count, C-reactive protein (CRP) and serum troponin concentrations than volunteers (p<0.05, p<0.01 and p<0.0001, respectively)." (PMID 28986407, 2018). "In myocarditis, serum biomarkers of inflammation such as leukocytes, erythrocyte sedimentation rate and C-reactive protein are often elevated." (PMID 29292734, 2017). "The younger age and higher C-reactive protein (CRP) values in myocarditis patients are in concordance with the literature." (PMID 28659139, 2017). "Combining troponins and CRP measurements, one study has found a sensitivity of 100% for myocarditis identification." (PMID 24587933, 2014). "Patients with acute myocarditis displayed elevated circulating IL-6 and C Reactive Protein levels, which correlated with significantly higher circulating C3, compared to healthy controls or to samples from DCM or chronic myocarditis." (PMID 23460527, 2013). "Five significantly younger patients (48 ± 32years;p < 0.05) with low incidence for cardiovascular risk factors (1.0 ± 0.1), low Wells (0.3 ± 0.7) but high serum levels of CRP (102 ± 81 mg/dl) revealed peri-/myocarditis on CMR." (PMID 20840783, 2010). "Aberrant type I interferon responses constitute a pathogenic hallmark of SLE and are usually associated with antiviral-like low-CRP responses, possibly suggesting that additional inflammatory pathways are overactivated in patients with SLE who develop myocarditis." (PMID 39047157, 2025). "Severe laboratory findings may help in the diagnosis of TB myocarditis,including elevated troponin and C-reactive protein (CRP) levels.Echocardiographic abnormalities may include regional wall motion or biventricular(global) dysfunction." (PMID 41356306, 2025). "Notably, patients with myocarditis were significantly younger, had lower BMI, higher CRP and CK levels, and more frequently presented with significant ST-segment elevations compared to other groups." (PMID 41341294, 2025). "Notably, CRP was substantially higher in (peri-) myocarditis (mean: 7.0 vs. 3.2 mg/dl, p < 0.001), consistent with an inflammatory pathogenesis." (PMID 41341294, 2025). "Inflammatory markers such as high-sensitivity C-reactive protein (hs-CRP) may also reflect ongoing myocardial inflammation or a prothrombotic state." (PMID 41465334, 2025). "Similarly, median WBC, ANC, CRP and procalcitonin values were higher in the fulminant myocarditis cohort (p < 0.001, for all)." (PMID 41235300, 2025). "Patients with arrhythmogenic right ventricular cardiomyopathy and non-dilated LV cardiomyopathy may exhibit elevated levels of C-reactive protein, especially during bouts resembling myocarditis." (PMID 39200108, 2024). "In patients with myocarditis associated with EBV infection, troponin (I/T), creatinine kinase, C-reactive protein, and B-type protein, among others, may be elevated, but blood work is nonspecific." (PMID 37292213, 2023). "CRP and TnI levels were higher in patients with myocarditis than in index patients (19 vs. 3 mg/L, P = 0.07 and 6,443 vs. 15 ng/L, P < 0.001, respectively) and family members with the DSP variant (19 vs. 3 mg/L, P < 0.001 and 6,443 vs. 3 ng/L, P < 0.001, respectively)." (PMID 37008330, 2023). "Chest pain was found to be prominent with dependency over the subset {Electrocardiogram ST segment elevation, Chest X-ray normal, Echocardiogram normal, Myocarditis, Electrocardiogram normal, C-reactive protein increased, Troponin increased} with a lift value of >8 (R3,5,7–9,11,13)." (PMID 35897804, 2022). "To the best of our knowledge, for the first time we report that the frequency of abnormal CRP levels at diagnosis is high, up to 70% from a large consecutive cohort of patients with biopsy-proven and clinically suspected myocarditis, strictly defined according to the 2013 ESC criteria." (PMID 36498643, 2022).
myocarditis (continued). "In cases of suspected clozapine-induced myocarditis, fever, tachycardia, shortness of breath, and chest pain were the most common symptoms, and C-reactive protein, eosinophil count, and troponin levels were elevated to varying degrees in more than half of the patients." (PMID 35873271, 2022). "Data regarding the diagnostic role and correlates of abnormal CRP levels in myocarditis are lacking." (PMID 36498643, 2022). "Thus, higher CRP levels identified patients with clinically suspected myocarditis with infarct-like presentation, which are known to have better functional status and a more favourable disease course." (PMID 36498643, 2022). "We hypothesized that NT-proBNP and CRP may predict the severity of the disease in acute myocarditis among patients with preserved or mildly reduced LVEF better than troponin." (PMID 35566598, 2022). "The aim of the current study is to examine the prognostic yield of the natriuretic peptide N-terminal-pro hormone Brain Natriuretic Peptide (NT-proBNP) and C-reactive protein (CRP) in acute myocarditis among patients with preserved/mildly reduced left ventricular ejection fraction (LVEF)." (PMID 35566598, 2022). "When myocarditis occurred, neutrophil to lymphocyte ratio, C-reactive protein, lactate dehydrogenase, interleukin (IL)-6, IL-10, creatine kinase, MB isoenzyme of creatine kinase, and brain natriuretic peptide increased from baseline, but absolute lymphocyte count decreased." (PMID 35924238, 2022). "However, it has to be pointed out that the sensitivity for highly sensitive CRP in detecting myocarditis was only 50.1% whereas the specificity was 80.7%." (PMID 33542341, 2021). "NLR and MLR showed a significant correlation with the length of hospital stay in patients with myocarditis, and were better predictive for prolonged hospital stay than established biomarkers like CRP, leukocyte count, high sensitivity troponin, creatinine kinase and pBNP." (PMID 34518607, 2021). "Indeed, the patients who developed acute myocarditis, aged 5 and 11 years old, had very high levels of C-reactive protein (CRP: 183 and 315 mg/L, respectively) and elevated liver enzymes (AST: 99 and 77 IU/L, respectively)." (PMID 32932612, 2020). "Also, in the Kawasaki disease shock syndrome acute myocarditis occurs in only 30% of the cases; platelets count, C-reactive protein and neutrophil count are lower than what we observe in our population." (PMID 32488505, 2020). "In our study, the inflammatory parameters, including ALB, PLT, ESR, and CRP, in unresponsive patients were all higher than in responders, which also suggested that the myocarditis in IVIG‐resistant patients may be more serious than in IVIG‐responsive patients." (PMID 31173382, 2019). "Also, the elevation of inflammatory markers and cytokines such as erythrocyte sedimentation rate, C-reactive protein, interleukin-1α, tumor necrosis factor and interferon gamma are often reported in myocarditis." (PMID 29292734, 2017). "Infact, CMR showed the presence of myocardial edema on STIR-T2W sequences and sub-epicardial necrosis on post-contrast T1W sequences; therefore, these imaging findings added to troponin I and CK-MB release and an elevation of CRP and white blood cells, strongly suggested an acute myocarditis." (PMID 27871237, 2016). "If this protocol had been applied to this case, the combination of gastrointestinal distress with tachycardia would prompt team to obtain troponin I and CRP levels (which would be ideally compared to baseline values) immediately, resulting in earlier discovery of the myocarditis." (PMID 26266072, 2015). "CRP, an inflammatory marker associated with myocarditis, did not exceed 0.50 mg/dL." (PMID 40697750, 2025). "Interestingly, in acute myocarditis, CRP is often stably normal or near normal and we might speculate that CRP is lower in cases of associated myocarditis." (PMID 39798014, 2025).
myocarditis (continued). "Importantly, the discriminative potential of these routine parameters was further supported by our ROC curve analyses: univariate analyses of age, BMI, CRP and CK levels, and significant ST-segment elevation individually demonstrated only modest predictive value for (peri-) myocarditis." (PMID 41341294, 2025). "Thus, CRP along with some other biomarkers with similar activities including TNF-alpha, troponin, and creatinine kinase are frequently used as diagnostic and prognostic markers of myocarditis along with the determination of its severity and progressive stages." (PMID 39564010, 2024). "Therefore, we tried to understand the correlation between CRP and myocarditis." (PMID 39564010, 2024). "In addition, the high frequency of clinically suspected myocarditis may have blunted the prognostic role of CRP." (PMID 36498643, 2022). "C-reactive protein was elevated in the majority of myocarditis patients but it should still be used as an ancillary feature, rather than a specific diagnostic and prognostic biomarker, as it did not identify myocarditis patients with worse clinical features." (PMID 36498643, 2022). "In our study, we suggest the three-parameter model, including the history of recent infection, an abnormal CRP value on admission > 5 mg/L, and the age of < 36 years, which might become a simple but essential tool for initial differentiation between acute myocarditis and MI in clinical practice." (PMID 35207189, 2022). "However, so far only weak correlations between organ-specific heart inflammation, i.e., myocarditis and endothelialitis, and systemic inflammation (as assessed by CRP and circulating serum cytokines) have been shown, both in ischemic and non-ischemic cardiomyopathies." (PMID 36498643, 2022). "The significant correlation between myocardial ECV and serum CRP level, as well as the significant correlation between myocardial and skeletal T2 values, may indicate that the degree of myocardial inflammation is positively correlated with the systematic inflammation level." (PMID 32272936, 2020). "• Estimation of markers of inflammation such as C-reactive protein, inflammatory markers such as the tumour necrosis factor α, and the plasma marker of apoptosis (Fas/Apo-1) may perhaps help in making a preliminary diagnosis of myocarditis." (PMID 23192260, 2012). "Inflammatory and immunohistochemical markers such as CRP, IL-6, fibronectin, desmin, complement C5b-9, and S100A1 contribute to the identification of early ischemia and myocarditis, particularly when routine histology is inconclusive." (PMID 41596321, 2026). "In acute myocarditis, sST2 was significantly better than those of TNI, NT-proBNP and CRP in predicting FM." (PMID 40098635, 2025). "All cases demonstrated elevated inflammatory markers, including C-reactive protein (CRP) and procalcitonin, and evidence of organ dysfunction, such as acute kidney injury, rhabdomyolysis, and myocarditis." (PMID 40248523, 2025). "However, CRP acts as a non-specific diagnostic biomarker for accurate diagnosis of myocarditis." (PMID 39564010, 2024). "Three different databases, i.e., PubMed, ScienceDirect and Google Scholar were searched with specific keywords such as “C-reactive protein,” “CRP,” and “myocarditis” with certain search techniques." (PMID 39564010, 2024). "The inflammatory markers like CRP and ESR, as well as BNP, were also elevated in myocarditis and pericarditis." (PMID 39456253, 2024). "Our findings suggest that in myocarditis cases, ST-segment elevation on ECGs predicts more damage to the myocardium—these patients had lower LVEF and higher CRP levels." (PMID 39452564, 2024). "As for laboratory investigations, troponin, B-type natriuretic peptide (BNP), and inflammatory markers (mainly C-reactive protein, CRP) should be performed in case of suspicion of acute myocarditis." (PMID 39767843, 2024). "In acute myocarditis, erythrocyte sedimentation rate (ESR) and C-reactive protein (CRP) are typically elevated." (PMID 35223280, 2022).
myocarditis (continued). "Serum lactate, C-reactive protein, serum troponin, natriuretic peptide, erythrocyte sedimentation rate (ESR), and procalcitonin are used to diagnose myocarditis." (PMID 35974860, 2022). "The greatest clinical value of CRP, besides prognostication, appears to lie in the distinction of true MINOCA from myocarditis mimicking MI." (PMID 34032303, 2021). "As the onset of myocarditis is typically within 14 – 22 days of the start of CLZ treatment, it is critical to closely monitor patients for fever, troponin I or T and CRP levels for the first 28 days of treatment." (PMID 29670504, 2018). "CRP levels were significantly higher in patients who had myocarditis after >10 years of SLE than patients without myocarditis and similar disease duration." (PMID 39047157, 2025). "We found that patients with myocarditis had increased haematocrit, AST, and CRP." (PMID 40535371, 2025). "Compared to the nonfulminant myocarditis group, the fulminant myocarditis group had significantly increased CRP, CK-MB, NT-proBNP, cTnI, ALT, AST, and Lac levels at admission (p < 0.05)." (PMID 41143176, 2025). "Univariate logistic analysis showed that WBC, NT-proBNP, Troponin I, CRP, albumin, hemoglobin levels and HALP score could predict fulminant myocarditis." (PMID 41235300, 2025). "Compared to the mild myocarditis group, the fulminant myocarditis group had higher age, NYHA scores, Neutrophil, cardiac troponin I (cTnI), CK-MB, BNP, CRP, lactic acid (Lac), aspartate aminotransferase (AST), alanine aminotransferase (ALT), serum creatinine (sCr), NPAR, SII, SIRI and AISI." (PMID 40927299, 2025). "Compared with patients with uncomplicated myocarditis, patients with complicated myocarditis exhibited elevated troponin and creatinine kinase levels and greater inflammation, as indicated by higher WBC counts and CRP levels." (PMID 38398340, 2024). "Myocarditis/pericarditis biomarkers include cardiac enzymes (troponin with or without creatinine kinase/CK-MB), inflammatory markers like C-reactive protein (CRP) and erythrocyte sedimentation rate (ESR) or hormones like brain natriuretic peptide, (BNP)." (PMID 39456253, 2024). "In our report, CRP was elevated in 8 patients (66.7%), 6 of whom had systemic symptoms, and all patients with myocarditis received a PD-1 inhibitor but not PD-L1 inhibitor treatment." (PMID 37089888, 2023). "Elevated levels of inflammatory biomarkers like C-reactive protein, serum lactate, troponin, and abnormal ECG may be helpful for high-index suspicion of myocarditis." (PMID 36420287, 2022). "Although the C-reactive protein level can be elevated in the acute phase, it is neither sensitive nor specific for detecting active myocardial inflammation." (PMID 36540482, 2022). "Nonspecific serum markers of inflammation including leukocytes and C-reactive protein were elevated in our case suggestive of acute myocarditis, but normal values do not exclude an acute myocardial inflammatory process." (PMID 36705185, 2022). "In another CMR-based study, the level of myocardial damage detected by CMR during acute myocarditis was positively correlated to the level of CRP while troponin level was not." (PMID 35566598, 2022). "In our cohort of clinically suspected and biopsy-proven myocarditis, CRP levels at diagnosis did not contribute to the predictive accuracy of the outcome using a machine-learning RF prediction model." (PMID 36498643, 2022). "Our data, along with previous studies support the prognostic value of CRP and NT-proBNP, but not troponin in the acute phase of myocarditis." (PMID 35566598, 2022). "Patients with fulminant myocarditis often present with advanced NYHA functional class secondary to massive myocardial necrosis and reduced LVEF, while in patients with mild disease, the dominant process is inflammation reflected by high CRP levels." (PMID 35566598, 2022).
myocarditis (continued). "In a cohort of 386 patients with myocarditis, 100% of patients were found with elevated Troponin T levels and 99% of patients were found with abnormal values of acute phase reactants, namely erythrocyte sedimentation rate (ESR) or C-reactive protein (CRP)." (PMID 35956137, 2022). "Elevated CRP, TnI and GLS in combination with TnI can be useful to detect myocardial inflammation." (PMID 33542341, 2021). "Four patients, ages 20 to 30, presented with myocarditis characterized by chest pain, elevations in troponin-I and C-reactive protein, and negative viral serologies two to four days following mRNA vaccine administration." (PMID 34396358, 2021). "Trends of slight elevation of ESR and CRP at baseline and a significant reduction of ESR after steroid therapy in the improved myocarditis group might support our hypothesis that inflammation preexisted and played role in its own pathogenesis." (PMID 33414828, 2020). "These symptoms should not be ignored especially when accompanied by CRP levels over 50 mg/L, which signify the onset of myocarditis." (PMID 29670504, 2018). "In contrast, subclinical myocardial inflammation, at least as reflected by hs-CRP concentrations, did not explain the tendency toward ventricular arrhythmias in our community-based cohort of relatively young subjects." (PMID 27875987, 2016). "Similarly, CRP and platelet counts did not emerge as independent predictors in our analysis, despite being elevated in fulminant myocarditis." (PMID 41235300, 2025). "The lack of association of CRP with biventricular function indexes found here and in previous work reinforces the lack of prognostic value of CRP, since biventricular function is an established independent predictor in clinically suspected and in biopsy-proven myocarditis." (PMID 36498643, 2022). "Our findings are in keeping with a recent study on a large cohort of idiopathic heart failure patients with immunohistochemically defined myocardial inflammation on EMB; myocardial inflammation was associated with higher CRP and troponin I levels, but CRP failed to predict prognosis." (PMID 36498643, 2022). "Based on our results, any increase in troponin should be a ‘red light’, and even non-severe rises of CRP might herald myocarditis." (PMID 35048875, 2021). "CRP was commonly elevated, although normal levels did not exclude myocarditis." (PMID 34206074, 2021). "Finally, healthy control participants did not undergo blood sampling, and thus inflammatory markers such as WBC count, NLR, and CRP could not be directly compared with those of myocarditis patients." (PMID 41497007, 2026). "Thus, an independent prognostic role of CRP remains unproven, particularly in consideration of the established and predominant independent negative prognostic role of reduced LVEF in myocarditis, which per se might account for the mortality association." (PMID 36498643, 2022). "However, this study does suggest that circulating CRP levels may not be a sensitive biomarker of cardiac microvascular and myocardial inflammation in HFpEF." (PMID 30114262, 2018). "In particular, multiple clues within the polymorphic VA group, namely fever, higher C-reactive protein, lower LVEF, and higher proportion of EMB-proven necrosis, are all indicators of an acute rather than chronic stage of myocarditis." (PMID 38130417, 2023). "Other findings suggestive of myocarditis include global dilation on ECHO, elevated inflammatory markers (ESR, C-reactive protein, etc.), and non-specific changes on EKG, which were not seen in our patient." (PMID 36183036, 2022). "Non-specific indicators, such as elevated C-reactive protein and ECG abnormalities (e.g., sinus tachycardia, ST-segment abnormalities), may support a diagnosis of myocarditis but are of limited specificity." (PMID 39759659, 2024).